TNF (tumor necrosis factor)
Diseases named in the same sentence as TNF in open-access papers (continued):
Sharing a sentence is not in itself a finding about the gene and the disease.
lupus (continued). "Articular symptoms were taken into account only if they reappeared with other lupus symptoms in a patient in whom they had previously disappeared under anti-TNF therapy and/or were different from previous complaints." (PMID 15899041, 2005). "TNF-α is a significant cytokine involved in lupus oral pathology." (PMID 40791585, 2025). "TNF‐ α inhibitors have unique structures that can induce immune responses, which may result in the development of paradoxical autoimmune phenomena, such as systemic lupus erythematosus (SLE)." (PMID 39816706, 2025). "Moreover, drugs such as etanercept, which target TNF-α, have been shown to reduce oral ulcers and improve overall oral health in lupus patients." (PMID 40791585, 2025). "Treatment with quercetin in murine lupus models was associated with kidney protection through the downregulation of inflammatory markers (TGF-β1, TNF-α, Bcl-2-associated protein x (Bax), IL-6) and counts of senescent T cell and follicular helper T cell subsets." (PMID 40852730, 2025). "We also treated kidney organoids with C3-LHF1 in the presence and absence of TNFα, a signaling molecule associated with progression of lupus pathologies." (PMID 41145914, 2025). "However, when we directly compared the epigenetically distinct groups of patients with lupus, only group 1 lupus individuals with disease-altered chromatin were enriched for TNF-α signaling." (PMID 39688922, 2024). "Notably, administration of exogenous TNF-α in spontaneous models of lupus in B/W mice, which have low endogenous TNF-α production, has shown a protective role for this cytokine in delaying the progression of renal disease." (PMID 39830664, 2024). "However, a much larger set of TFs contained in the TNF-α signaling gene set appeared among the active TFs in lupus cells; these include FOSL1, KLF6, RELB, BHLHE40, EGR3, and SMAD3." (PMID 39688922, 2024). "DARs showing increased accessibility in lupus were enriched for programs including lymphocyte activation, T cell activation, and multiple Hallmark cytokine signaling pathways, including those of IFN-γ, TNF-α, and IFN-α." (PMID 39688922, 2024). "Similarly, TNF-α, a key systemic and neuroinflammatory mediator, is increased in human lupus CSF, as is MCP-1, which attracts monocytes and microglia to sites of inflammation." (PMID 38600510, 2024). "Many genes contained in the Hallmark IFN-α response and Hallmark TNF-α signaling pathways, including IFI27, IFI44, RELB, KLF6, and CD83, had significantly higher expression in lupus: We verified transcriptional changes in the naive compartment by quantitative PCR (qPCR)." (PMID 39688922, 2024). "Clinical review linked reduced TNF-α signaling enrichment and absence of the lupus chromatin state in group 2 patients to ARB prescription." (PMID 39688922, 2024). "It was reported that the protein expression of pro-inflammatory cytokines like TNFα and IL-1β, and ERK activity, were increased in the DRG in lupus mice with chronic pain, which were also associated with increased excitability in nociceptive sensory neurons in the DRG." (PMID 38612414, 2024). "In addition, CB exhibits broader-spectrum activity in purified pDCs and in a lupus mouse model, significantly reducing levels of pro-inflammatory cytokines IL-1β, IL-17, TNF-α and the interferon-regulated gene TRAIL, both in vitro and in vivo." (PMID 39737176, 2024). "In FcγRIIb−/− lupus mice, TNFα expression in macrophages was elevated." (PMID 38164134, 2023). "Therefore, paying attention to the cytokine microenvironment and immunological context present in lupus (high levels of IL-6 and TNF-α) can probably partially justify the results observed in this study." (PMID 38072921, 2023). "However, addition of a TNFRI-neutralizing antibody to TNFα-treated lupus mice induced less BMSCs within the lungs but more BMSCs homing to the lymph node and spleen." (PMID 38164134, 2023).
lupus (continued). "Nowadays, it is still unclear whether TNF-α inhibitors play a role in the exacerbation of systemic lupus erythematosus." (PMID 36836166, 2023). "Increased renal expression of TNF-α was observed in lupus mice." (PMID 36946374, 2023). "The expression of CLEC4D was associated with an up-regulated pathway of Neutrophil extracellular trap formation, PPAR signaling pathway, Staphylococcus aureus infection, Systemic lupus erythematosus, TNF signaling pathway, and Toll−like receptor signaling pathway." (PMID 36979470, 2023). "However, TNF-α and IL-17 are found in increased titers in lupus patients compared to the general population." (PMID 37833861, 2023). "When this occurs, it is thought to be anti-TNF-α-induced lupus." (PMID 37833861, 2023). "Importantly, expression of pro-inflammatory cytokines (IL-1β, IL-6, TNFα and IFNγ) was increased in PVAT from lupus mice, concomitant with elevated plasma levels of TNFα, IFNγ and IL-6." (PMID 37006244, 2023). "Blood transcriptomic analysis revealed that the pathways of BS-Z15 secondary metabolites affecting immune function in mice were mainly enriched in the TLR signaling pathway, response to interferon-β, tumor necrosis factor signaling pathway, systemic lupus erythematosus, and primary immunodeficiency." (PMID 37208602, 2023). "Lupus serum and its IgG activated Syk and NF-κB signaling, resulting in the release of TNF-α." (PMID 35273604, 2022). "The incidence and course of systemic lupus erythematosus (SLE) differ between the sexes, with a nine-fold higher incidence in women linked to the influence of estrogen on epigenetic, immune and genetic factors (X-linked genes such as Foxp3, TNF and Tlr7)." (PMID 35203537, 2022). "Systemic lupus erythematosus induced by biologics mainly results from tumor necrosis factor-alpha remains unclear." (PMID 35733860, 2022). "This protective effect seems to be associated with the significantly decreased production of IL-6 and TNF-α, indicating that abnormally activated autophagy in macrophages may contribute to lupus by promoting the production of TNF-α and IL-6." (PMID 35456038, 2022). "In our enrichment analysis, TNF signaling pathway was also enriched, indicating that TNFAIP3 and other members of TNF signaling pathway might play a role in the pathogenesis of lupus and LN." (PMID 36275661, 2022). "In patients with higher levels of circulating TNFα, there are also increased PEV numbers indicating that TNFα may be stimulating PEV production in lupus." (PMID 35887184, 2022). "Paradoxically, anti-TNF-α agents have been successfully used to treat lupus, so the exact mechanism of this reaction, for now, remains unknown." (PMID 36145514, 2022). "In another study, increased expression of Tim-1 protein protected podocytes in lupus-prone mice by inhibiting the IgG-induced inflammatory response in podocytes and reducing tumor necrosis factor α (TNF-α), interleukin (IL)-6 and IL-1β expression, and inducing autophagy." (PMID 35457062, 2022). "DHA can also improve lupus symptoms in BXSB mice by inhibiting the production of TNF-α." (PMID 35592412, 2022). "Moreover, TNF-α and IL-6 are also important for lupus exacerbation as the potent pro-inflammatory cytokines in macrophage and neutrophil activation." (PMID 35897790, 2022). "Studies have shown that artemisinin can alleviate the levels of interleukin-6 (IL-6) and tumor necrosis factor-α (TNF-α) in the plasma of mice with systemic lupus erythematosus and inhibit the activities of nuclear factor‐kappa B (NF-κB) and transforming growth factor-β1 (TGF-β1) in the kidney." (PMID 35370688, 2022). "Clinical characteristics of patients with TNF-α inhibitor-induced systemic lupus erythematosus." (PMID 35733860, 2022). "Anti-TNF-α induced lupus usually disappears after stopping the offending drug." (PMID 33802483, 2021).
lupus (continued). "In addition, since the CD90+αSMA+ mesangial cells are an important source of proinflammatory cytokines like IL‐6 and TNF‐α in kidney, the reduced mesangial cells in IL‐35p and Tregs‐treated lupus mice indicate an immunoregulatory functions of IL‐35 in vivo." (PMID 33634995, 2021). "There is evidence that endogenous antibodies to TNFα may be important in control of disease activity in systemic lupus erythematosus, raising the possibility that AMG 966 may have value as a therapeutic vaccine." (PMID 34970265, 2021). "We hypothesize that the Th1 subset is one of the main targets of the mutant sNASP and contributes to the lupus pathogenesis, and the variant leads to uncontrolled IFN-γ and TNF-α transcription." (PMID 34720750, 2021). "Moreover, TNF-α treatment deteriorated lupus manifestation and progression in MRL/lpr and BXSB strains." (PMID 33572870, 2021). "The first line of therapy of anti-TNF-α-induced lupus is the withdrawal of the offending drug." (PMID 34336341, 2021). "The constructed PPI network with these DE-mRNAs identified 38 hub genes mostly enriched in pathways related to systemic lupus erythematosus, alcoholism, viral carcinogenesis, osteoclast differentiation, adipocytokine signaling pathway and tumor necrosis factor signaling pathway." (PMID 33868359, 2021). "We found that IL-6 and TNF-α production by B cells from IRF5-heterozygous mice was reduced by about half in response to combinations of stimuli that are thought to be involved in B cell activation in the GC in lupus." (PMID 34197340, 2021). "B cell–intrinsic IL-6 and TNF-α production have been shown to be important in GC formation in mice immunized with T-dependent antigens and in GC formation and disease pathogenesis in lupus and other autoimmune models." (PMID 34197340, 2021). "Importantly, the inhibition of HA in lupus-prone mice improved disease parameters, at least partially by reducing the expression of pro-inflammatory cytokines, including IL-1β, TNFα, and IL-6, in the kidney." (PMID 33240280, 2020). "However, TNF-α inhibitors do not consistently work for sarcoidosis and are also complicated in SLE treatment due to the fact that TNF-α inhibitors can induce lupus." (PMID 33324666, 2020). "In systemic lupus erythematosus, it was reported that TNF-α could be protective, since its levels and TNF-α/IL-10 ratio were lower in patients with active disease." (PMID 31906962, 2020). "For example, IFN-α and TNF-α encapsulated in EVs from patients with systemic lupus erythematosus (SLE) are significantly higher than in healthy individuals, which means that detection IFN-α and TNF-α levels in EVs of patients can be used as novel diagnostic markers of SLE." (PMID 33072123, 2020). "Lupus IgG promotes the GC response through TNF-α production by macrophages." (PMID 32082297, 2019). "TNF-α is important for the development of skin and liver injuries induced by lupus serum." (PMID 32082297, 2019). "In addition to clinical evidence, in vivo murine models demonstrated the protective effect of TNF in lupus development, showing improvement in survival rate and renal damage after the administration of TNF to lupus-prone NZB/NZW F1 mice." (PMID 31052273, 2019). "In addition to delaying lupus disease manifestations, fish oil reduced the expression of IL-1β, TNF-α, and ICAM-1 in (NZB x NZW)F1 (BW) mice, while it increased the expression of antioxidant enzymes." (PMID 31137916, 2019). "Lupus IgG activated Syk and NF-κB signaling, leading to the release of TNF-α." (PMID 32082297, 2019). "It is thus notable that TNF-α is elevated in plasma of silica-exposed (NZBxNZW)F1 lupus mice." (PMID 31632407, 2019). "According to previous research, miR-339-5p inhibited the expressions of the proinflammatory factors IL-6, IL-1β, and TNF-α by abolishing NF-κB activity and miR-361-5p is downregulated in interferon-positive antiphospholipid syndrome and systemic lupus erythematosus dendritic cells." (PMID 30854012, 2019).
lupus (continued). "Since lupus IgG increased the level of TNF-α in the supernatant of BMMs, we speculated that lupus IgG could promote GC formation through the secretion of TNF-α by macrophages." (PMID 32082297, 2019). "However, in systemic lupus erythematosus, TNF-α can induce the expression of PD-L1 in mononuclear cells, while TGF-β has the opposite effect." (PMID 30646912, 2019). "TNF-α plays an important role in the liver damage induced by lupus IgG." (PMID 29988500, 2018). "This lower TNF-α was found in a depressive status of systemic lupus erythematosus." (PMID 30314474, 2018). "TNF-α was positively correlated with triglycerides in lupus group (r = 0.519, p = 0.023)." (PMID 29316941, 2018). "In addition, we also found that depletion of NK cells in TNF-α−/− mice almost completely abolished the hepatic inflammation following lupus IgG administration." (PMID 29988500, 2018). "TNF is already targeted by biologic therapeutic approaches, and IFN regulatory factors 3 and 7 (IRF3 and IRF7) have been implicated in the IFN signature in lupus previously." (PMID 27846842, 2016). "African American women with lupus also had a higher level of TNF-α (p = 0.0427)." (PMID 26583155, 2015). "Thus active anti-cytokine immunization with Kinoid appeared to be feasible in humans against TNF as shown here and also against IFNα as previously reported in lupus patients." (PMID 25517733, 2014). "A second hypothesis is that TNF α inhibitors suppress the T-helper type 1 response, resulting in a T-helper type 2 response; this leads to autoantibody production and lupus-like features." (PMID 24949211, 2014). "The role of tumor necrosis factor alpha (TNFα) and its inhibition in lupus is debated." (PMID 24528782, 2014). "Low levels of TNF-α mRNA can be detected in lupus-prone mice prior to renal injury." (PMID 24171032, 2013). "TNFα secretion that participates in inflammatory processes characterizes lupus progression." (PMID 22247763, 2012). "Finally, as also observed using MRL/lpr peripheral blood lymphocytes (PBLs), NCS 613 inhibits basal and LPS-induced TNFα secretion from PBLs of lupus patients, suggesting a therapeutic potential of NCS 613 in systemic lupus." (PMID 22247763, 2012). "The mechanisms by which anti-TNFα therapy induces lupus remain unclear but are likely to differ from classic DILE." (PMID 22937775, 2012). "Although previous studies have demonstrated that lupus monocytes produce substantially higher levels of TNF-α upon stimulation with LPS or immune complexes, this is the first study that shows that this abnormal pattern of cytokine production can be induced by apoptotic cells." (PMID 21423726, 2011). "Thus, for example, known genetic polymorphisms and/or epigenetic changes at the TNF-α locus associated with SLE may contribute to this cytokine pattern in lupus monocytes." (PMID 21423726, 2011). "The incidence of anti-TNF-induced lupus is difficult to evaluate." (PMID 15899041, 2005). "However, this does not exclude the possibility that the TNF blockade merely revealed an underlying predisposition to lupus." (PMID 41375587, 2025). "However, in some cases, in addition to discontinuing anti‐TNF therapy, corticosteroids and immunosuppressive agents might be required to achieve full resolution of lupus symptoms." (PMID 39816706, 2025). "The average time to onset of lupus‐like paradoxical reactions (L‐PRs) is approximately 14.6 months, although onset may occur in less than 1 month or extend beyond 6 years after initiation of TNF‐α inhibitor therapy." (PMID 39816706, 2025). "TNF levels are increased in SLE, but the role of TNF in SLE remains controversial with studies reporting associations with disease activity, but also induction of SLE or lupus-like disease as a result of exposure to anti-TNF agents." (PMID 41117951, 2025). "However, we identified a patient subgroup prescribed angiotensin receptor blockers (ARBs), which lacked TNF-linked lupus chromatin accessibility features." (PMID 39688922, 2024).
lupus (continued). "A 56‐year‐old gentleman presented for evaluation of white‐matter lesions in the context of TNF‐induced systemic lupus erythematosus (SLE)." (PMID 37476595, 2023). "Patients with SLE have higher serum TNF-α levels, which correlate with disease activity and many systemic manifestations, such as SLE-related cardiovascular disease and lupus nephritis." (PMID 37833861, 2023). "Thus, TNFα contributes to lupus development in vivo and in vitro." (PMID 38164134, 2023). "Consistent with this, HLA-DR2/DQw1-positive SLE patients have been demonstrated to show low TNF-α production and an increased incidence of lupus nephritis." (PMID 35884790, 2022). "Although relatively uncommon, this finding may caution the use of TNF-neutralizing agents in lupus." (PMID 35486723, 2022). "In Systemic Lupus Erythematosus (SLE) and other autoimmune diseases, LDNs are highly inflammatory, produce type I interferon and activate T cells to produce TNFα and type II interferon." (PMID 34168640, 2021). "A host of reports on spontaneous and induced lupus models pointed to the onset of SLE associated with high levels of IFN-γ and TNF-α." (PMID 34720750, 2021). "Furthermore, CTSS-overexpressing mice showed a marked increase in the production of IL-17, TNF-α, IFN-α and IFN-γ, which are known to be associated with lupus development, and the chemoattractants CCL2, CCL7 and CCLl12, which are activated by IFN-α to attract monocytes to inflammatory sites." (PMID 34381063, 2021). "In addition, it may provoke severe side effects such as anti-TNF-α-induced lupus or hepatitis, even though it is rare." (PMID 33333788, 2020). "T cells from SLE patients and lupus-prone mice have expanded T helper 1 (Th1), Th17, follicular, and extrafollicular helper T (Tfh and eTfh) cell subsets, which contribute to the inflammation and autoreactive antibody production through increased IFNγ, TNFα, IL-6, IL-17, and IL-21 secretion." (PMID 32849532, 2020). "Ustekinumab is well-tolerated in adult and pediatric patients for treating psoriasis, psoriatic arthritis, systemic lupus erythematosus (SLE), and Crohn's disease, and has shown lower immunogenicity compared to most anti-TNF agents." (PMID 30740105, 2019). "Importance of TNF-α in P. falciparum malaria and systemic lupus erythematosus (SLE) have been demonstrated." (PMID 31409832, 2019). "While LPS tolerance affected only TNF-α and IL-6 production in wild-type macrophages, LPS tolerance also impaired other pathogen control mechanisms (phagocytosis and microbicidal activity) in FcGRIIb−/− cells as a mechanism possibly responsible for the significant LPS exhaustion in lupus." (PMID 30889825, 2019). "However, it not known whether TNF reaches high systemic levels or if these lupus-traits are TNF dependent." (PMID 31354711, 2019). "In a murine lupus model induced by lupus serum, Il-1r-deficient mice and caspase-1-deficient mice demonstrated major improvements in skin inflammation, with decreased expression of MCP-1 and TNF-α, indicating inflammasome pathways contribute to skin inflammation of LN." (PMID 31427885, 2019). "Childhood-onset systemic lupus erythematosus (c-SLE) is a chronic autoimmune disease which increases cardiovascular risk factors (CRF) such as elevated homocysteine, TNF-α, and hs-C reactive protein." (PMID 29316941, 2018). "For example, the highly connected TF IRF5 is associated with multiple autoimmune diseases, including multiple sclerosis and systemic lupus erythematosus (SLE), and leads to low type-I interferon, TNF and IL6 production in knockout mice." (PMID 30184180, 2018). "Type I interferons (IFN), such as interferon-alpha (IFN-α), and proinflammatory cytokines such as tumor necrosis factor-alpha (TNF-α) play an important role in the pathogenesis and disease progression of systemic lupus erythematosus (SLE)." (PMID 28367002, 2017).